EPHA2 (EPH receptor A2)
Diseases named in the same sentence as EPHA2 in open-access papers (continued):
Sharing a sentence is not in itself a finding about the gene and the disease.
cancer (continued). "This approach is especially promising for cancers that overexpress specific receptors, such as HER2, EGFR, or EphA2, allowing immunotoxins to deliver highly potent agents selectively." (PMID 39685591, 2024). "The expression of PTK2, USP19, LAMC2, VEGFA, EPHA2, and MMP2 varies greatly among different cancer samples and has relatively high expression." (PMID 38694917, 2024). "Mechanistically, EphA2 has been shown to regulate the CDK2/Cyclin E1/2 complex via the proteasome-mediated degradation of p27^KIP1, thereby inhibiting cancer cell growth." (PMID 38612592, 2024). "Synergistic interaction between the EphA2 inhibitor ALW and the HDAC inhibitor panobinostat was observed in vitro to lead to enhanced DNA damage and impaired cancer cell survival." (PMID 38279277, 2024). "Phosphorylation of serine/threonine residues in Eph receptors can trigger ligand-independent signalings, as exemplified by S897-phosphorylated EphA2, which activates AKT and PI3K, promoting the migration and invasion of cancer cells." (PMID 38811954, 2024). "Specifically, even in early-stage cancer, there was a notable difference between healthy individuals and patients with Stage I CRC (p = 0.00298), highlighting the potential of EphA2 as a biomarker for early detection." (PMID 39766211, 2024). "In cancer cells, where ADAM17 is highly expressed and active, ADAM17 directly cleaves ephrin-A1 and thereby disrupts EphA2/ephrin-A1 binding." (PMID 36998455, 2023). "Another newly identified stress-induced antigen that is recognized by Vδ1 TCR is ephrin type-A receptor 2 (EphA2), which is upregulated upon AMP-activated protein kinase (AMPK)-dependent metabolic reprogramming of cancer cells." (PMID 35747139, 2022). "In our dataset, in addition to EPHB1, we also identified EPHA1, EPHA2 and EPHA7 that were highly phosphorylated in cancer compared to normal tissue, making these proteins as potential therapeutic targets." (PMID 36093296, 2022). "We have identified that multiple RTKs, such as EGFR, FGFR2, EPHA2, and MET, are key targets for C1GALT1 and their appropriate O-glycosylation is essential for cancer progression and metastasis." (PMID 35169131, 2022). "Certain studies have also indicated that EphA2 favors the Epithelial–Mesenchymal Transition (EMT) and contributes to the preservation of cancer stem cell-like characteristics." (PMID 36142306, 2022). "This section discusses six shedding examples that influence cancer progression, namely, CD44, ICAM-1, DDRs, syndecans, EphA2, and HB-EGF." (PMID 36132127, 2022). "The same EphA2 residue is phosphorylated by ionizing radiation in a MEK/ERK/RSK-dependent manner, mediated by increased ROS, in multiple cancer cell lines." (PMID 33572284, 2021). "Extracellular cleavage of EphA2 by MT1-MMP can enhance cell repulsion and single-cell invasion of cancer cells." (PMID 33947097, 2021). "In addition, the tyrosine kinase EphA2, which belongs to the family of Eph tyrosine kinase receptors, is highly expressed in tumors, while it has been found at relatively low levels in most normal adult tissues, indicating its potential application in cancer treatment." (PMID 34631854, 2021). "Silencing of EphA2 decreased S6K1-mediated phosphorylation of the cell death agonist BAD, resulting in increased apoptosis of the cancer cells." (PMID 33572284, 2021). "By immunoblotting of patient‐derived cells, EphA2 (total and phosphorylated), GPRC5A, and RSK showed variable expression in the cancer cells, whereas GPRC5A was undetectable and RSK low in patient‐derived CAFs." (PMID 32115889, 2020). "Many factors, including EphA2, Notch4, VE‐cadherin, SLPI, TWIST, VEGF, vimentin and HIF‐1α, are related to the formation of VM in many cancers." (PMID 33118329, 2020).
cancer (continued). "In fact, downstream target molecules of EPHA2, including FAK/Src kinases, are critical regulators of the cancer progression and a pronounced increase of active FAK/Src form expression associates with the PROX1 knock-down." (PMID 31060342, 2019). "The expression of EPH receptor A2 (EPHA2) is activated by EGFR and EGFRvIII in the human cancer cell lines." (PMID 29423044, 2018). "Target gene candidates in cancer therapy are mainly involved in oncogenes, angiogenesis and proliferation, like PLK1, EphA2, RRM2, KRAS, PKN3 and VEGF, which have been tested as target genes in early-phase clinical trials for RNAi-based cancer therapies." (PMID 30065155, 2018). "While the expression of EphA1 and EphA2 increases in early stages of CRC, the abundance of these receptors decreases in advanced stages of the cancer." (PMID 29682554, 2018). "If EphA2 is expressed in these tissues, this would eliminate it as a potential target for ADC cancer therapies." (PMID 22370972, 2013). "In addition to serving as a direct target, EphA2 could be used as a cancer-related protein for antibody-targeting therapy, particularly antibody-drug conjugate (ADC)-based therapies, in which chemical toxins or radioligands are covalently added to the antibody structure." (PMID 22370972, 2013). "Our finding of EFNA1 in the conditioned media of HeLa cells indicates that, like many cancer cells, HeLa cells express EFNA1 in addition to EPHA2, and that some of the EFNA1 is released from the cell surface of these cells." (PMID 20979646, 2010). "Exposure to ligand mimetics (ephrinA1-Fc) has been shown trigger rapid EphA2 phosphorylation and receptor downregulation in MDA-MB-231 breast and PC-3 prostate cancer cells." (PMID 18797457, 2008). "The EPHA2, EPHA3 and EPHA4 have been found correlated with a variety of cancers, including lung carcinoma, prostate carcinoma, colon carcinoma, pancreatic carcinoma, ovarian carcinoma, thyroid carcinoma, tongue carcinoma, hepatocellular carcinoma, glioma and melanoma." (PMID 40919148, 2025). "The Eph receptor family is the largest receptor tyrosine kinase family, and EphA2, as a member of the Eph receptor family, exhibits LLPS characteristics in the occurrence and progression of various cancers, including colorectal cancer, liver cancer and breast cancer." (PMID 40231263, 2025). "EphA2-79 and EphA2-85 CAR-T cells recognized EphA2 and killed the target cancer cells." (PMID 40181964, 2025). "Δ Ecto, EphA2-79, and EphA2-85 CAR-T cells, and target cancer cell lines were cocultured to measure interferon (IFN)-γ, tumor necrosis factor (TNF)-α, and Granzyme B, cytokines secreted via killing target cancer cells, using ELISA." (PMID 40181964, 2025). "Our results provide a strong rationale for clinical investigation of EphA2 inhibitor or its downstream inhibitor in patients having ESCC with PT fusions, which might also be useful in other types of cancers exhibiting PT fusions, besides ESCC." (PMID 40615663, 2025). "In contrast, the ephrin-A-independent non-canonical signaling of EphA2 plays a critical role in cancer progression." (PMID 40236294, 2025). "EPHA2 and FLT4 have been investigated as promising targets for cancer treatment." (PMID 39818967, 2025). "EPHA2 plays a substantial role in the broad landscape of the EPH receptor tyrosine kinase family, particularly in relation to the metastasis of a wide spectrum of cancers." (PMID 39797421, 2025). "Specifically, it was found that phosphorylation at residue S897 within the EphA2 intracellular domain leads to the activation of downstream signaling mechanisms in cancer cells without requiring a ligand–receptor interaction." (PMID 39056783, 2024). "Additionally, tropomyosin-related kinase A (TrkA) recruits EphA-2, which subsequently enhances BCA cell invasion; conversely, TrkA inhibition reverses cancer cell migration." (PMID 38612592, 2024).
cancer (continued). "In contrast to brain invasion, liver invasion by MDA-MB-231 TrkA KD cancer cells was not impaired following EphA2 inhibition." (PMID 38072918, 2023). "A large proportion of driver oncogene products are known to constitutively activate the ERK-RSK pathway; therefore, constitutive non-canonical EphA2 activation often occurs in various types of human cancer cells." (PMID 37059179, 2023). "Recent studies have shown that Epha2-SE deletion leads to decreased EphA2 expression, which inhibits Wnt/β-catenin and PI3K/AKT pathway activation, thereby inhibiting the invasion and migration of cancer cells, including MCF-7 cells, HCT-116 cells, and HeLa cells." (PMID 37501079, 2023). "Therefore, many researchers are developing cancer treatments targeting EGFR, K-Ras, Ras-downstream effectors, and EphA2." (PMID 35668076, 2022). "We found significant enrichment of RAE1, a SE60 cis direct target, and EPHA2, a SE14 cis direct target, within the cancer cell fraction as compared to the normal cell fraction (Wilcoxon Rank Sum tests, Bonferroni-corrected p-values < 2.2e−308 and average logFC ≥ 0.1)." (PMID 35869079, 2022). "Further studies confirm the crosstalk between EPHA2 and EGFR signaling in cancer." (PMID 36297233, 2022). "Their results not only highlight the key role of exosomal EPHA2 in transmitting an aggressive phenotype among cancer cells, but also suggest that they do not rely, entirely, on direct cell-to-cell contact." (PMID 35408909, 2022). "This treatment may be a useful treatment for other kinds of cancers that have high expressions of BIRC5 and EphA2." (PMID 36439089, 2022). "EphA2 non-canonical signaling is often elevated in cancer cells and promotes their oncogenic properties, including epithelial-mesenchymal transition, invasiveness and metastasis, mechanotransduction, stem cell-like properties, and drug resistance." (PMID 34857764, 2021). "EphA2 promotes cancer malignancy through a poorly understood non-canonical form of signaling involving serine/threonine phosphorylation of the linker connecting its kinase and SAM domains." (PMID 34857764, 2021). "We performed RT-qPCR and confirmed the differential expression of several cancer driver genes: increased mRNA expression of oncogenes MYC and PIK3CG, as well as decreased expression of tumor suppressor genes CDKN1A and EPHA2, was observed in the H2BE76K mutant cells." (PMID 33548228, 2021). "EPHA1 and EPHA2 proteins expression, although lower in cancer tissues compared with matched non-malignant ones, was observed as higher in metastatic lesions than in primary tumor specimens." (PMID 34445116, 2021). "Our findings indicate the key functional role of exosomal EphA2 in the transmission of aggressive phenotype between cancer cells that do not rely on direct cell–cell contact." (PMID 33879771, 2021). "Furthermore, our analysis based on previous pan-cancer proteomic data also demonstrated that EGFR and EPHA2 are the most positive correlated with MYOF across different types." (PMID 34178975, 2021). "Confocal microscopy showed EPHA2 localization at the cell-cell junctions in primary cells, but not in cancer cell lines." (PMID 33596248, 2021). "Collectively, these results highlight the key functional role of exosomal EphA2 in the transmission of aggressive phenotype between cancer cells that do not rely on direct cell–cell contact." (PMID 33879771, 2021). "In contrast, EPHA2 expression was not confined to cell-cell junctions in cancer-derived organoids, rendering it accessible to EBV." (PMID 33596248, 2021). "We found the highest EphA2 expression in solid tumors including prostate (DU-145), colon (HT-29), and renal (A-498) carcinoma cell lines in contrast to mostly negative hematological cell lines." (PMID 34691070, 2021). "Samples were considered EphA2-positive if ≥10% of cancer cells were stained positive for EphA2, irrespective of staining intensity." (PMID 33092175, 2020).
cancer (continued). "Despite EphA2 overexpression in cancer, phosphorylated EphA2 is found in lower amounts in cancer cells in comparison with non-transformed epithelial cells." (PMID 32811512, 2020). "Two additional genes known primarily for their contribution to angiogenesis, VEGFR2 (KDR) and Ephrin A2 (EPHA2), were lowly expressed by the human cancer cells and did not change in response to aspirin treatment." (PMID 32246008, 2020). "Several EphA2-specific T cells have been developed and evaluated in preclinical studies, recognizing EphA2-expressing tumors as assessed by interferon-γ (IFN-γ) and IL-2 synthesis and conferring cancer cell cytotoxicity." (PMID 32811512, 2020). "In addition, the activated EphA2 proteins also directly activate PI3K, which then promotes the MMP precursor to form MMPs, ultimately promoting the cancer cell binding to form VM channels." (PMID 30723742, 2019). "Notably, the same study demonstrated that a combined targeting of FAP+ CAFs and EPH receptor A2 (EphA2)+ cancer cells led to a nearly complete remission of the tumors, suggesting that CAF or PSC targeting can synergize with cancer-cell killing." (PMID 31108941, 2019). "Therefore, cancer‐related RTK become preferable targets for ADC development, e.g. RON, PTK7, FLT3, FGFR2, FGFR3, ERBB3, KIT and EPHA2." (PMID 31116512, 2019). "Here we investigate the role of the EphA2 SAM domain in several cancer model cell lines with and without ligand stimulation." (PMID 28338017, 2017). "In parallel with this we show that RCP and EphA2 are required for efficient invasion and metastasis in an in vivo model of PDAC suggesting that cell-cell repulsion is an important step in the metastatic spread of cancer." (PMID 28294115, 2017). "The flow cytometry data, performed with polyclonal antibodies against whole proteins rather than internal domains, indicated that EphA2 is at least as abundantly present on living cancer cells as EphB4." (PMID 28165374, 2017). "In addition, the activated VE-Cad and EphA2 proteins also directly activate PI3K, which then promotes the MMP precursor to form MMPs, ultimately promoting the cancer cell binding to form VM channels." (PMID 26429872, 2015). "This review focuses on EphA2 functions that have not been reviewed previously, and its roles in tumorigenesis and cancer are not discussed since the several acceptant reviews in this area have been published recently." (PMID 24705208, 2013). "Body-wide expression profiles for EPHA2, VEGFC, and ERBB3 indicated the most selective overexpression in malignant connective tissues, when compared to all other pediatric cancer and healthy normal tissues." (PMID 23227212, 2012). "EphA2 is an RTK involved in cancer development and progression, especially when in its non-phosphorylated state." (PMID 20955590, 2010). "In the end, this preliminary computational study highlights that the relationship to cancer of certain SASH1-Sam1 mutations (like the Y659C and D661H) could be due to negative modulation of the SASH1-Sam1/EphA2-Sam association." (PMID 39942820, 2025). "Therefore, anti-EphA2 mAbs can target cancer cells, which activate the non-canonical EphA2 signaling." (PMID 40236294, 2025). "FUT1 targets the fucosylation of CD147, intercellular adhesion molecule 1 (ICAM-1), EGFR, and EPH receptor A2 (EPHA2), consequently converging on the down-regulation of AKT/mTOR/eukaryotic translation initiation factor 4E-binding protein 1 (4EBP1) signaling to enhance cancer stemness." (PMID 40821120, 2025).
cancer (continued). "IHC showed that expression levels of both USP5 and EphA2 in the cancer tissues were significantly higher than those in the normal tissues, and USP5 levels were positively correlated with EphA2 levels in cancer tissues, supporting USP5 as the deubiquitinase of EphA2 in NPC." (PMID 39897046, 2025). "This discrepancy may help explain the malignancy of cancer cells, as the abundant expression of EphA2 on the cell surface enables the triggering of non-canonical signaling that promotes cancer cell growth." (PMID 40236294, 2025). "In addition, we found that cis direct target genes annotated for each SE (such as RAE1 and EPHA2) were more highly expressed in the cancer cells compared to the stromal/non-malignant cells within HGSOC tumors." (PMID 35869079, 2022). "However, cancer mutations of this particular leucine have not been reported for EphA2 (cbioportal.org), an Eph receptor that is highly expressed in many cancer types." (PMID 34139238, 2021). "In contrast, in cancer-derived organoids as well as cell lines, EPHA2 was not restricted to cell-cell contacts but also present at apical and basal sides of the cells, implying that this could possibly be an entry site." (PMID 33596248, 2021). "As an EphA2 tyrosine kinase inhibitor, whether ALW-II-41-27 inhibits cancer progression by inhibiting pY772-EphA2 has not been explored." (PMID 32848131, 2020). "EphA2 was abundant in RCP immunoprecipitates, and we confirmed its co-precipitation with endogenous and GFP-tagged RCP (irrespective of whether EphA2 or RCP was the bait), in a range of cancer cell lines." (PMID 28294115, 2017). "Next, to evaluate whether proNGF stimulation modulates the capacity of cancer cells to interact with the BBB, the transmigration capacities of MDA-MB-231 TrkA and TrkA KD cells through the BBB were quantified along with the impact of EphA2 inhibition on this phenomenon." (PMID 38072918, 2023). "However, the sole clinical trial incorporating a NSCLC patient could not describe objective anti-cancer effects after anti-EPHA2 antibody administration." (PMID 36613532, 2022). "Interestingly, a combined targeting of FAP+ CAFs and EPH receptor A2 (EphA2)+ cancer cells led to a nearly complete remission of the tumors, suggesting that CAF-targeted approaches have the potential to supplement and synergize with conventional cancer-cell-targeted therapies." (PMID 31417869, 2019). "Thus, our study results do not preclude ADC cancer therapies targeting EphA2 as yet." (PMID 22370972, 2013). "Although EPHA2 inhibitors have not yet been tested specifically in GCA, their effectiveness in related cancers suggests potential applicability in treating GCA with EPHA2 mutations." (PMID 39792765, 2025). "EPHA2/EFNA1 had a positive correlation in PNI and a negative correlation in non-PNI cancer compartments." (PMID 40075699, 2025). "Many malignant tumors exhibit cell motility, EMT, and drug resistance because of constitutive non-canonical activation of EphA2 through the MEK-ERK pathway upon growth factor stimulation." (PMID 39466050, 2024). "In non-tumorous (histologically normal) tissues from cancer patients, there were correlations between TIE2 and FGFR1, EPHA2 and VGFR3, FGFR3 and PGFRA (p < 0.05)." (PMID 36890818, 2023). "The constitutive non-canonical activation of EphA2 via the MEK-ERK pathway regulates the malignant progression of various tumors, including cancer cell motility, EMT, stemness properties, and drug resistance." (PMID 37059179, 2023). "Therefore, we suggest that EphA2 and EphA4 can signal via Vav2 and RhoA leading to microtubule destabilisation and subsequently cell–cell repulsion, although we cannot rule out additional signalling events regulating cancer cell repulsion downstream of EphA receptors." (PMID 24795148, 2014).